EXT1 (exostosin glycosyltransferase 1)
Diseases named in the same sentence as EXT1 in open-access papers (continued):
Sharing a sentence is not in itself a finding about the gene and the disease.
cancer (continued). "As the impact of WNT signalling pathway has been emphasized in the other non‐cancer cell lines, we seek to investigate whether the EXT1 promotes cancer progression by WNT signalling pathway." (PMID 33565239, 2021). "Based on these results, we suggest that EXT1 could be a promising novel target to overcome cancer cell stemness in anthracycline-based therapeutic resistance." (PMID 29050299, 2017). "In addition, to confirm that EXT1-mediated enrichment of cancer cell stemness in MCF7/ADR is specifically due to increased cell surface HS, MCF7/ADR cells were maintained in HS-containing media for 15 days before the experiments." (PMID 29050299, 2017). "Regarding clinical actionability, the EXT1 variant has implications for differential diagnosis, the BRCA1 variant for therapy selection, and both the BRCA1 and the BRIP1 variants are clinically relevant for risk assessment, prevention, prophylaxis and early detection of their associated cancers." (PMID 36550207, 2023). "To evaluate the clinical relevance of EXT1 and EXT2 in the context of therapeutic responses, we analyzed drug sensitivity correlations using the Genomics of Drug Sensitivity in Cancer (GDSC) database." (PMID 41438585, 2026). "This duplication also recurrently affected known cancer census genes such as CSMD3, COX6C, EXT1, FAM135B, MYC, and NDRG1 in SG1 and SG3 in more than 75% of patients." (PMID 36129940, 2022). "These implicate that S-scores and N-scores can allow one to find another type of biomarkers such as EXT1, PTCH1, KLK10, APC, TRIM13 that have strong information sensitive to early cancer." (PMID 33580150, 2021). "At stage 3, STARD13, CBFA2T3, RECK, and SASH1 had strong accordant/discordant effects on expression of genes in cancer, while APC, EXT1, NBL, KLK10, and PTCH1 had very weak accordant/discordant impacts on expression of genes in cancer." (PMID 33580150, 2021). "We observed overexpressed EXT1 in MCF7/ADR cells can facilitate and regulate cancer cell stemness, including increased ALDH+and CD44+/CD24- population, and growth of larger and more numerous mammospheres in MCF7/ADR cells." (PMID 29050299, 2017). "In particular, we identified that MCF7/ADR cells with highly expressed EXT1 increased EMT and cancer cell stemness, thus facilitating anchorage-independent colony formation in soft agar." (PMID 29050299, 2017). "Transcriptional patterns of HS-metabolic enzymes (EXT1, EXT2, NDST1, NDST2, GLCE, 3OST1/HS3ST1, SULF1, SULF2, HPSE) were determined in normal, benign, and cancer human prostate tissues and cell lines (PNT2, LNCaP, PC3, DU145)." (PMID 24782989, 2014). "This study investigated Exostosin-1 (EXT1), a key enzyme in heparan sulfate (HS) biosynthesis, as a mechanistic bridge connecting inflammation, stromal remodeling, and immune evasion-driven cancers." (PMID 42232599, 2026). "If true, the number of genes that could potentially modify cancer proliferation via FGF signaling is much larger than currently appreciated, expanding from EXT1 and EXT2 to all aminoglycan synthesis genes." (PMID 30573688, 2018). "Finally, we found major differences among the cancer cell lines in their expression of genes involved in glycosylation, including CHST11, CHST13, Ext1, HAS2 and HAS3, which may have an impact on the architectural organization of the spheroids." (PMID 39011470, 2024). "Although our study did not analyze the expression of Ext1 and Ext2 in cancers in detail, it is suggested that changes in the expression of Ext1 or Ext2 in cancers may contribute to the differences in cancer development in this study." (PMID 36809261, 2023). "EXT1 is involved in the biosynthesis of HS and HS is reported to be involved in various developmental and inflammatory processes; however, its role in carcinogenesis and cancer cell stemness is not known." (PMID 29050299, 2017).
cancer (continued). "Furthermore, knockdown of EXT1 not only repressed cancer cell stemness but also downregulated EMT markers and abolished cell surface HS, suggesting EXT1 as a potential molecular target to overcome cancer cell stemness in doxo-mediated therapeutic resistance." (PMID 29050299, 2017). "Indeed, except for that PTCH1, KLK10, TBRG1, NBL1 and EXT1 did not act on gene expression in stage-2 cancer, the other 21 TS gene had larger positive network effects on gene expression than negative network effects in cancer." (PMID 33580150, 2021). "At stage 3, however, all these 26 defined TS genes have S > 0, suggesting that all these 26 TS genes had larger positive network effects on gene down-expression in cancer than negative network effects on gene up-expression even though APC, EXT1 and DDX5 had very small S-scores." (PMID 33580150, 2021). "The integration sites at the two hotspots, chr1: 34,397,059 (CSMD2) and chr8:118,557,327 (MED30/EXT1), were not reported in previous HBV integration studies (except in this dataset as we previously reported), but overlapped with multiple fusion events from both cancer cell lines and TCGA." (PMID 35710421, 2022).
infection (6 papers, 2010 to 2025). The state of being infected such as from the introduction of a foreign agent such as serum, vaccine, antigenic substance or organism. "Different amounts of plasmid encoding EXT1 were transfected into HEK-293 cells, followed by infection with ZIKV." (PMID 39927690, 2025). "To investigate whether the cell surface TvBspA625 protein is expressed during infection we measured the presence of antibody recognizing the four peptides (EXT-1/2, and CT-1/2) in sera from patients infected by T. vaginalis and contrasted these to control sera from T. vaginalis negative patients." (PMID 20144183, 2010). "To determine whether sulfated GAGs or sulfated proteins are critical for SAFV-3 infection, we established SLC35B2 KO and EXT1 KO HeLa-N cell lines (referred to as HeLaN-∆SLC and HeLaN-∆EXT1, respectively)." (PMID 41397982, 2025). "Knockout of EXT1, a gene essential for heparan sulfate synthesis, also inhibited SARS-CoV-2 infection via ACE2 and TMEM106B, confirming the supporting role of heparan sulfate for both infection routes." (PMID 37421949, 2023).
autosomal dominant disease (4 papers, 2010 to 2022). Autosomal dominant form of disease. "As stated in the introduction, the clinical diagnosis of the autosomal dominant disease of MO is often made without genetic testing, as in previous studies, a germline mutation in the EXT1 or EXT2 gene was found in almost 90% of cases." (PMID 35103870, 2022). "MHE, autosomal dominant disease, links with exostosin 1 (EXT1) and 2 (EXT2) genes." (PMID 25520924, 2014). "Peak heights were normalized against 3 reference probes (EXT1, CREBBP and EP300), selected from known autosomal dominant disease genes, which would not be deleted or duplicated without an obvious phenotype." (PMID 20957197, 2010).
skeletal dysplasia (2 papers, 2024). Any Mendelian diseases that affects growth and development of the skeleton. "Therefore, the severity of skeletal dysplasia is correlated with the genotype, as patients with EXT1 mutations are more severely affected than those with EXT2 mutations." (PMID 39030613, 2024).
EXT1 also shares sentences with these, for which no sentence is quoted: Type 2 diabetes (3 papers); Cognitive impairment (2); developmental delay (2); liver cancer (2); trichorhinophalangeal syndrome (2); Alzheimer disease (1); amyloid (1); anaplastic astrocytoma (1); Anorexia (1); Anxiety (1); astrocytoma (1); benign tumors (1); bone cancer (1); brain cancer (1); cardiomyopathy (1); chronic lung disease (1); cognitive decline (1); crescentic glomerulonephritis (1); diabetes (1); endothelial dysfunction (1); fibrodysplasia ossificans progressiva (1); geleophysic dysplasia (1); genetic disorder (1); Hajdu-Cheney syndrome (1); hamartoma (1); hematologic cancer (1); hereditary multiple osteochondromas (1); hereditary tumor syndromes (1); Immune Diseases (1); lymph node metastasis (1).
A further 22 diseases each share a sentence with EXT1 in 1 paper.